SRGAP2B (SLIT-ROBO Rho GTPase activating protein 2B)
Description:
May regulate cell migration and differentiation through interaction with and inhibition of SRGAP2. In contrast to SRGAP2C, it is not able to induce long-lasting changes in synaptic density throughout adulthood.
Synonyms: SRGAP2P2; SRGAP2L
Tractability: PROTAC: ubiquitination databases record sites on it.
Gene: Protein-coding gene on chromosome 1 (144,887,191 to 145,095,528, reverse strand). Ensembl gene ENSG00000196369.
Subcellular location (Human Protein Atlas): Basal body; Centrosome; Cytosol
Gene Ontology:
Molecular function: GTPase activator activity
Biological process: regulation of synapse assembly; negative regulation of cell migration; nervous system development
Cellular component: glutamatergic synapse; dendritic spine
Genetic constraint (gnomAD): Loss-of-function variants: 2 observed, 2.6 expected, observed/expected ratio (o/e) 0.77, 90% interval 0.3 to 1.8. That is too few expected variants to judge how well the gene tolerates losing a copy. Missense variants: 26 observed, 23.37 expected, observed/expected ratio (o/e) 1.11, 90% interval 0.81 to 1.54. Synonymous variants: 7 observed, 9.02 expected, observed/expected ratio (o/e) 0.78, 90% interval 0.44 to 1.45.
Homologues: Orthologues: macaque SRGAP2 (99% identical), mouse Srgap2 (98% identical), rat Srgap2 (98% identical), dog SRGAP2 (90% identical), tropical clawed frog srgap2 (86% identical), zebrafish srgap2 (86% identical), Caenorhabditis elegans srgp-1 (28% identical). Paralogues in human: SRGAP2 (99% identical), SRGAP2C (98% identical), SRGAP1 (78% identical), SRGAP3 (69% identical), ARHGAP4 (45% identical).